RRM2 (ribonucleotide reductase regulatory subunit M2)
Diseases named in the same sentence as RRM2 in open-access papers (continued):
Sharing a sentence is not in itself a finding about the gene and the disease.
glioblastoma (31 papers, 2011 to 2026). The most malignant astrocytic tumor (WHO grade IV). "What is more is that we successfully identified RRM2 as a novel biomarker linked with prognosis, which might be expected to be a promising target for the therapy of glioblastoma." (PMID 31119182, 2019). "The analysis indicated that glioblastoma patients exhibiting genomic alterations in PCNA clamp-associated factor (PCLAF), RRM2, nucleolar and spindle-associated protein 1 (NUSAP1), and KIF23 displayed reduced overall survival rates, as shown in Fig.." (PMID 39248068, 2025). "And the prognostic significance of RRM2 has been documented in various cancer types, including pancreatic cancer and glioblastoma." (PMID 39256879, 2024). "RRM2 is a promising therapeutic target for glioblastoma, and the use of triapine can effectively target RRM2, making glioblastoma cells more sensitive to radiation and inducing synthetic lethality when combined with checkpoint kinase 1 inhibition." (PMID 40625451, 2024). "Another study in glioblastoma showed that BRCA1 regulates RRM2 expression via E2F1, and RRM2 inhibition mimics the phenotype of BRCA1-loss in glioblastoma cells." (PMID 38124207, 2023). "Our results showed that PECT can induce G2/M phase cell cycle arrest and increase autophagic flux of glioblastoma cells by inhibting RRM2 expression, which can be reversed by RRM2 overexpression plasmid." (PMID 35651787, 2022). "In human glioblastoma, RRM2 promoted cell proliferation, migration, and invasion, and reduced apoptosis." (PMID 33858512, 2021). "Overexpressed RRM2 promotes invasiveness in gastric cancer and inhibits cell apoptosis in human glioblastoma." (PMID 33858512, 2021). "BRCA1-regulated RRM2 expression protects glioblastoma cells from endogenous replication stress and promotes tumorigenicity." (PMID 31886214, 2019). "For example, RRM2 protected glioblastoma cells from endogenous replication stress, DNA damage, and apoptosis; RRM2 inhibition sensitized glioblastoma cells to agent treatment." (PMID 30898978, 2019). "Here, the authors find that BRCA1 promotes the expression of RRM2 protecting glioblastoma cells from replication stress, DNA damage and apoptosis." (PMID 27845331, 2016). "Particularly, RRM2 and KIF23, with the highest node degrees of 22, were closely associated with poorer overall survival rates, underscoring their potentially critical roles in glioblastoma oncogenesis." (PMID 39248068, 2025). "Moreover, alterations in RRM2 and KIF23 were associated with diminished disease-free survival rates for glioblastoma patients, as illustrated in Fig.." (PMID 39248068, 2025). "At present, the clinical management of glioblastoma, chronic granulocytic leukemia, acute granulocytic leukemia, and sickle cell anemia has incorporated the utilization of inhibitors that specifically target RRM2, yielding favorable therapeutic outcomes." (PMID 39256879, 2024). "In human glioblastoma, RRM2 inhibits cell apoptosis, promoting tumor progression." (PMID 40625451, 2024). "In the present study, we found that pectolinarigenin inhibits glioblastoma proliferation, increases autophagic flux, and induces cell cycle arrest by inhibiting ribonucleotide reductase subunit M2 (RRM2), which can be reversed by RRM2 overexpression plasmid." (PMID 35651787, 2022). "Hence, the overexpression of RRM2 in glioblastoma could predominantly result from gene amplification, a hypothesis that warrants further investigation for validation." (PMID 39248068, 2025). "On the other hand, RRM2 discriminated untreated GBM from normal nervous system; this is embedded in the TCGA clinical data of histological_type but it can also be considered as a typical comparison between glioblastoma and normal brain tissue." (PMID 34204789, 2021).
glioblastoma (continued). "In future studies, we may combine gene expression levels of RRM2 and KIF23 and cell biological behavior analysis to further explore the oncogenesis of glioblastoma." (PMID 39248068, 2025). "RRM2 knockdown promoted the degradation of CDK1 protein through autolysosome-dependent pathway by increasing autophagic flow, thereby inhibiting the proliferation of glioblastoma by inducing G2/M phase cell cycle arrest." (PMID 35651787, 2022). "Indeed, in glioblastoma-derived cells, BRCA1 knockdown downregulates RRM2, a catalytic subunit of ribonucleotide reductase, leading to replication stress and DNA damage, and ultimately suppressing cell proliferation." (PMID 33888730, 2021). "Whereas 5FU and gemicitabine also inhibit RRM2 (ribonucleoside-diphosphate reductase M2 subunit) and DHFR (dihydrofolate reductase), the new drug raltitrexed may be more specific to TYMS, but no published data are available for glioblastoma treatment." (PMID 21365010, 2011).
melanoma (25 papers, 2012 to 2025). A malignant, usually aggressive tumor composed of atypical, neoplastic melanocytes. "The CDKN2A mutated melanoma cells are expected to be more sensitive to RRM2 inhibitor cladribine that was in clinical development for multiple sclerosis and leukemia, as reported by SLKG." (PMID 33627666, 2021). "On the other hand, ribonucleotide reductase (RRM2) has been associated with TMZ resistance in melanoma cells in vitro." (PMID 34676045, 2021). "Melanoma patients exhibited the highest frequency of RRM2 alterations, with “mutation” being the predominant type, whereas the “amplification” type of CNA and copy number “deep deletion” were the predominant types in LIHC and Mature B-cell Neoplasms, respectively." (PMID 36518297, 2022). "Therefore, co-expression of TS, RRM1 and RRM2 in melanoma cells partially overcomes senescence caused by C-MYC depletion." (PMID 23249808, 2012). "Researchers conducted another study on the melanoma cell line A375, which exhibits elevated ribonucleotide reductase regulatory subunit M2 (RRM2) expression." (PMID 39482766, 2024). "We chose melanoma cell lines, A375, for investigation because of the high RRM2 mRNA expression level." (PMID 38992695, 2024). "al revealed that targeting the USP7/RRM2 axis drives senescence and sensitizes melanoma cells to HDAC/LSD1 inhibitors." (PMID 38635758, 2024). "RRM2 gene expression was found to be correlated with tumor grade in both breast and epithelial ovarian malignancies and poor overall survival in melanoma." (PMID 36811764, 2023). "H-Ras induces senescence of human fibroblasts and melanoma cells by inhibiting ribonucleotide reductase regulatory subunit M2 (RRM2), which regulates deoxyribonucleotide triphosphate (dNTP) metabolism." (PMID 35892977, 2022). "We found that idebenone treatment in UBIAD1KD cells can significantly restore expression of these markers in all melanoma cell lines tested (except for RRM2 in Mel Juso), supporting the functional role of CoQ10 in UBIAD1-dependent melanoma survival." (PMID 35255427, 2022). "We performed a pan-cancer analysis of the genetic alteration status of RRM2 and observed that maximum alteration (> 4%) appeared in patients with endometrial carcinoma; patients with primary type of melanoma showed an alteration frequency of ~3%." (PMID 36202136, 2022). "Silencing RRM2 attenuated melanoma growth, which was consistent with the maintenance of senescence-associated cell-cycle arrest." (PMID 34384030, 2021). "Treatment with 0.2 mm HU increased activated pCHK1 Ser317 and CHK1 activity (demonstrated by elevated RRM2 levels) in panels of melanoma TSs and NSCLC cell lines, but had little effect on pRPA2 S4/8 and γH2AX levels." (PMID 31044505, 2019). "Melanoma cells depleted of TS and RRM2 demonstrated substantial DNA damage (detected by antibodies to phosphorylated histone H2AX [H2AX-γ]) and increased activity of SA-β-Gal." (PMID 23249808, 2012). "Based on in vivo results, the exosome-delivered siRNA silencing RRM2 demonstrated noticeable melanoma growth regression, suggesting the RNA-targeted exosome delivery system with RRM2siRNA could attenuate tumor growth." (PMID 38992695, 2024). "Moreover, RRM2 gene overexpression has been found in breast, ovarian, gastric, bladder, colorectal cancers, and melanoma." (PMID 36811764, 2023). "Additionally, we found that patients with RRM2 high expression achieved clinical benefits of PD-1 immunotherapy in melanoma and hence exhibited prolonged OS and PFS in the Riza2017_PD1 clinical study." (PMID 35740608, 2022). "Some of the limitations of GTI2040 can be avoided in CALAA‐01 by encapsulating RRM2‐specific siRNA within nanoparticles, and its efficacy has been evaluated in phase I clinical trials in patients with melanoma; however, sufficient evidence for the antitumor effects of CALAA‐01 is lacking." (PMID 34319001, 2021).
melanoma (continued). "Taken together, our data indicate that depletion of dNTPs is one of the major causes of DNA damage and senescence in MYC-depleted melanoma cells and that maintaining high TS, RRM1 and RRM2 levels is important for C-MYC-dependent suppression of senescence programs in these cells." (PMID 23249808, 2012). "In melanoma, RRM2 could enhance melanoma grow and promote cellular senescence." (PMID 38356717, 2024). "The results revealed that RRM2 expression was significantly increased in most cancer groups, including bladder, brain, breast, cervical, colorectal, esophageal, gastric, head and neck, kidney, liver, lung, lymphoma, melanoma, ovarian, pancreatic, prostate, and sarcoma cancers." (PMID 38635758, 2024). "Similarly, DEPDC1B SHCBP1, RRM2, PLK1, and UHRF1 have been found to promote melanoma proliferation and could be potential targets for treatment; their coefficients were all positive, which implies that they had an additive effect on the risk scores." (PMID 34384498, 2021).
non-small cell lung carcinoma (23 papers, 2008 to 2025). A group of at least three distinct histological types of lung cancer, including non-small cell squamous cell carcinoma, adenocarcinoma, and large cell carcinoma. "It is also worth mentioning that not only the dNTP amount but also the NTP amount was reduced when RRM1 or RRM2 was knocked-down in the H23 non-small cell lung cancer cells." (PMID 37513740, 2023). "For example, LINC00667/miR-143-3p axis controls Non-Small Cell Lung Cancer progression through targeting RRM2." (PMID 34895038, 2021). "Recently, it was shown that knockdown of RRM2 led to intrinsic apoptosis in head-and-neck squamous cell carcinoma and non-small cell lung cancer cell lines, confirming our findings." (PMID 31900418, 2020). "Interestingly, RRM2 is involved in miR-520a-mediated inactivation of the Wnt/β-catenin pathway during the development of non-small cell lung cancer." (PMID 35609318, 2022). "Moreover, miR-139-5p can suppress cell proliferation and chemotherapy resistance of non-small-cell lung cancer by inhibiting RRM2." (PMID 33954179, 2021). "The elevated expression of RRM2 may lead to the poor prognosis for patients with non-small cell lung cancer by stabilization of Bcl-2, which is a critical regulator of apoptosis." (PMID 31043166, 2019). "For example, USP12 could deubiquitinate RRM2 and promote non-small cell lung cancer progression." (PMID 38605077, 2024). "Studies have shown that RRM2 is known as a marker that may be involved in predicting clinical response to gemcitabine plus docetaxel and predicting the treatment response to platinum-based chemotherapy and survival in non-small-cell lung cancer patients." (PMID 31886214, 2019). "In Huang’s study on non-small cell lung cancer, the results showed that AFAP1-AS1 up-regulated RRM2 by inhibiting miR-139-5p expression, which in turn promoted the proliferation and chemotherapy tolerance of NSCLC cells." (PMID 41333212, 2025). "We have retrospectively examined the effect of RRM1, RRM2 and BRCA1 expression on outcome to gemcitabine plus docetaxel in advanced non-small-cell lung cancer (NSCLC) patients." (PMID 19002265, 2008). "Additionally, the lncRNA actin filament-associated protein 1 antisense RNA 1 (AFAP1-AS1) activates AKT signalling by upregulating RRM2 and subsequently promotes CDDP resistance in non-small cell lung cancer (NSCLC)." (PMID 34893064, 2021). "The expression levels of RRM2 and differences between primary tumors and infiltrated regional lymph nodes were correlated with relapse-free survival (RFS) and overall survival (OS) in patients with resectable non-small-cell lung cancer." (PMID 31886214, 2019).
renal carcinoma (22 papers, 2020 to 2025). A carcinoma arising from the epithelium of the renal parenchyma or the renal pelvis. "In renal cancer, RRM2 was dramatically overexpressed in tumor tissue, causing poor prognosis of cancer patients." (PMID 38356717, 2024). "We previously analyzed a TKI resistance dataset (GSE76068) from a mouse model and showed that RRM2 is closely associated with sunitinib resistance in renal cancer, and this effect is mediated by its activation of the AKT signaling pathway." (PMID 35280681, 2022). "(2021) on renal cancer (RCC) highlights the broader implications of RRM2 and ANXA1 beyond their traditional roles." (PMID 40744683, 2025). "RRM2 regulated antitumor immune responses, and knockdown of RRM2 enhances the antitumor efficiency of programmed cell death protein 1 blockade in renal cancer." (PMID 40625451, 2024). "Subsequently, we constructed stable renal cancer cells with RRM2 knockdown and IKBKE overexpression and found that the effect of IKBKE overexpression on cell proliferation and apoptosis was diminished in shRRM2 cells." (PMID 39664571, 2024). "Collectively, these findings indicate that IKBKE physically interacts with and phosphorylates RRM2 to activate the AKT signaling pathway in renal cancer." (PMID 39664571, 2024). "ANXA1, a protein involved in inflammation and apoptosis, has been identified as a mediator of RRM2-induced sunitinib and PD-1 blockade resistance in renal cancer." (PMID 37968699, 2023). "Another study provided evidence that knockdown of RRM2 enhances the antitumor efficiency of sunitinib and anti-PD-1 therapy in renal cancer, which further supported the potential role of RRM2 as a target to facilitate therapeutic resistance." (PMID 37596700, 2023). "RRM2 modulates the anti-tumor effect of sunitinib and PD-1 blockade in renal cancer by stabilizing ANXA1." (PMID 36678567, 2023). "Meanwhile, a recent article reported that RRM2 overexpression reduced sunitinib sensitivity in renal cancer." (PMID 36202136, 2022). "A similar result was reported in a study, wherein RRM2 overexpression reduced sunitinib sensitivity in renal cancer patients." (PMID 36202136, 2022). "Inhibition of RRM2 enhanced the antitumor effect of PD-1 blockade in renal cancer by promoting CD8+ T cell infiltration." (PMID 36612193, 2022). "We have shown that RRM2 is closely associated with antitumor immune responses and that the RRM2/ANXA1/AKT axis promotes PD‐L1 expression in renal cancer cells." (PMID 34319001, 2021). "Consistent with previous findings, RRM2 overexpression promoted tumor growth and sunitinib resistance in renal cancer by regulating hypoxia and AKT pathway activation." (PMID 34319001, 2021). "Furthermore, we found that RRM2 depletion mitigated the alterations in the IC50 values of sunitinib induced by either the overexpression or knockdown of IKBKE in renal cancer cells." (PMID 39664571, 2024). "Colony formation and Annexin V/7AAD staining assays demonstrated that RRM2 silencing could abolish the damaging effects of IKBKE on renal cancer cell growth and apoptosis." (PMID 39664571, 2024). "RRM2 is a well-studied oncogene that promotes cancer cell growth, migration, invasion, and chemoresistance in malignancies, such as retinoblastoma and breast, pancreatic, and renal cancers." (PMID 35609318, 2022). "Moreover, RRM2 regulated antitumor immune responses, and knockdown of RRM2 enhance the anti‐tumor efficiency of PD‐1 blockade in renal cancer." (PMID 34319001, 2021). "Notably, altering IKBKE expression did not further influence cell growth or sunitinib sensitivity when RRM2 was knocked down in renal cancer cells, demonstrating that IKBKE primarily modulates cell growth and sunitinib sensitivity through the RRM2-mediated AKT pathway." (PMID 39664571, 2024). "Besides, some researchers reported that RRM2 could regulate immunotherapy responses, and the knockdown of RRM2 could enhance the anti-tumor efficiency of PD-1 blockade in renal carcinoma." (PMID 36202136, 2022).
renal carcinoma (continued). "CYT387 treatment decreased the expression levels of both IKBKE and RRM2 in renal cancer cells, and 5 μM CYT387 markedly inhibited renal cancer cell growth." (PMID 39664571, 2024). "Consistently, we found that CYT387 treatment resulted in the downregulated expression of both IKBKE and RRM2, and CYT387 effectively inhibited renal cancer cell proliferation and arrested the cell cycle at the G2/M checkpoint." (PMID 39664571, 2024). "There are some basic experimental studies on the biological function of two target genes (RRM2 and BNIP3) regulated by FRlncRNAs for renal cancer." (PMID 35350243, 2022). "In conclusion, our results suggest that RRM2 overexpression in renal cancer cells plays a key role in sunitinib resistance in patients with RCC and that RRM2 competes with UBE3A to bind to the C‐terminus of ANXA1, preventing ANXA1 degradation." (PMID 34319001, 2021). "Meanwhile, the function of RRM2 in renal cancer has been validated, so we did not select renal cancer to conduct further validation." (PMID 35740608, 2022). "In consistence, we previously demonstrated that RRM2 could stabilize ANXA1 to activate PI3K/AKT signaling and lead to ICIs and sunitinib resistance in renal cancer." (PMID 35081978, 2022). "Moreover, we found that RRM2 interacted with and stabilized ANXA1 in renal cancer cells by competing with UBE3A." (PMID 34319001, 2021). "In addition, from our data it can be noticed that knockdown of RRM2 failed to further decrease AKT S473 phosphorylation in renal cancer cells with co‐knockdown ANXA1." (PMID 34319001, 2021). "Importantly, IKBKE knockdown could not further decrease the proliferation of renal cancer cells in the context of RRM2 silencing." (PMID 39664571, 2024). "Importantly, IKBKE knockdown could not further decrease the angiogenesis of renal cancer cells in the context of RRM2 silencing, and RRM2 silencing attenuated the effect of IKBKE overexpression on angiogenesis." (PMID 39664571, 2024).